CXCL10 (C-X-C motif chemokine ligand 10)
Diseases named in the same sentence as CXCL10 in open-access papers (continued):
Sharing a sentence is not in itself a finding about the gene and the disease.
tumor (continued). "This supports the idea that tumour-producing CXCL10 is able to recruit CXCR3+ infiltrating cells, including CD4 T cells, CD8 T cells, and NK cells." (PMID 34956172, 2021). "In the large majority of tumor types, Il12b, Ifng, Ccl4, Ccl5, Cxcl9, and Cxcl10 showed a significant positive correlation with infiltration of M1 macrophages, with Ccl3 displaying a lesser overall correlation." (PMID 34446712, 2021). "High tumor expression of c-Met and high basal serum levels of HGF, IL-6, CXCL11 and CXCL10 were significantly associated with reduced PFS and/or OS." (PMID 34200459, 2021). "Chemokine levels of CCL5 and CXCL10 were remarkably increased in supernatants of tumor tissues after combined incubation with curcumin and PIC." (PMID 33809574, 2021). "CXCL10 is known to drive the infiltration of immune cells into the tumour bed and was previously reported to bind to CXCR3 only." (PMID 33801414, 2021). "Among IFNγ targets, the chemokine CXCL10 has been shown to control T-cell recruitment into the tumor environment." (PMID 34220848, 2021). "Thereafter, we performed cellular functional assays to identify the role of CXCL10 in tumor cell activities." (PMID 34544905, 2021). "Inactivation of the machinery down-regulates T cell recruitment chemokines CXCL9 and CXCL10, and remodels a more favorable microenvironment for tumor growth." (PMID 34853298, 2021). "Increased levels of CXCL9 and CXCL10 have been reported to be related to elevated tumor CD8+ T cell density and improved survival in patients with a variety of cancers." (PMID 34249711, 2021). "In the same manner, FIP200 null cancer cells showed enhanced entrance of CTL within the tumor via elevated levels of CXCL10, which resulted in decreased primary tumor growth." (PMID 34944772, 2021). "Dendritic cells play critical roles in antigen presentation, cross-priming and activation of cytotoxic T cells, and produce CXCL9 and CXCL10 to recruit tumor-specific T cells to the tumor sites." (PMID 34579759, 2021). "Next, we were struck by the facts that, even at baseline (WT tumors), the concentrations of CXCL9 and CXCL10 in tumor extracts were greater than those of other cytokines by one or two orders of magnitude." (PMID 33664349, 2021). "We propose using stabilized forms of two of them: CXL9 and CXCL10, to enhance anti-tumor immunity and possibly transform cold tumors into hot ones." (PMID 34944943, 2021). "Our analysis revealed that IFNγ induces a selective and significant expression of CXCL10 in tumor cells." (PMID 33406104, 2021). "Inhibition of EZH2 and DNMT1 by chemical inhibitors restored the expression of CXCL9 and CXCL10 and increased effector T cell tumor infiltration." (PMID 34262562, 2021). "These M1 macrophages induce myeloma tumor cell death by activation of the intrinsic apoptotic pathway, and secrete CXCL9 and CXCL10, two angiostatic chemokines that contribute to the control of tumor development." (PMID 33435306, 2021). "Th1 cells, CD8+ T cells, and NK cells are also the major sources of IFN-γ, which induces the production of CXCL9 and CXCL10 by DCs and other tissue cells in the tumor microenvironment." (PMID 34885241, 2021). "The expression of CXCL10 in sensitive tumor tissues is significantly up-regulated at different time points of treatment compared with resistant tumor tissues (Wilcoxon signed-rank test, *** P < 0.001)." (PMID 34158843, 2021). "Our study sheds new light on the complexity of the chemokine network and the potential role of CXCL10 regulation by ACKR2 in tumour immunology." (PMID 33801414, 2021).
tumor (continued). "After therapeutic surgery, CXCL10 was found to be negatively associated with high levels of CD8 T cell infiltration, indicating poor tumor growth and recurrence." (PMID 33912192, 2021). "Particularly, CXCR3 chemokine receptor, along with ligands CXCL9 and CXCL10, is a major regulator of T cells infiltration to target tumor cells." (PMID 34572592, 2021). "Among the inflammatory mediators, cytokines IL-1α, IL-1β, IL-6, and IL-8 and chemokine CXCL10 were highly expressed, suggesting a function of CAFs in tumor-mediating inflammation." (PMID 34298873, 2021). "During anti-tumor responses, CD8 effector T cells readily infiltrate B16F10 tumors in a CXCR3-dependent manner in response to CXCL9 and/or CXCL10 expressed by both tumor cells and CD11c+ cells." (PMID 34362825, 2021). "This in turn induces tumor cells and T cells to secrete CXCL10, mediating the recruitment of CXCR3+ T cells from the periphery." (PMID 33406104, 2021). "Such infiltration resulted from the induction of STAT1 and IRF7, and the expression and secretion of pro-inflammatory chemokines and cytokines (CCL5, CXCL10, and interferon-γ) in tumor cells in vitro and tumor plasma in vivo." (PMID 34681622, 2021). "According to the multiples of differential expression, the expression level of tumor tissues, and the importance of biological functions in tumors, CXCL10 was selected for in-depth discussion." (PMID 34794429, 2021). "In short, a better understanding of CXCL10 in TME is required to understand its role in tumor progression and treatment." (PMID 34276760, 2021). "In further studies, comparing such expression separately using multiplex immunohistochemistry in whole tumor sections would provide a better understanding the role of CXCL10 in tumor progression." (PMID 34504204, 2021). "CXCL9 and CXCL10 are notably context-dependent; they have both an autocrine tumorigenic effect on tumor cells and a paracrine antitumor effect on infiltrating lymphocytes and macrophages depending which cells are expressing its receptor, CXCR342." (PMID 34433873, 2021). "CXCL10 is produced by many tumor cells and is found in high concentrations in a few human diseases and cancers." (PMID 34345201, 2021). "It is somehow puzzling that cancer cells also produce CXCL9 and CXCL10 and that this correlates with a better prognosis, in part due to the induction of anti-tumor CD4+ and CD8+ T cells." (PMID 34944943, 2021). "TNF, IFNγ and CXCL10 levels were significantly increased in plasma of mice with RM-1 tumors compared to tumor naïve mice." (PMID 33786638, 2021). "Because the number of tumor samples differed from the number of normal samples, we used matched paired analysis to determine the expression of CXCL10 in normal and tumor tissues from the same patient." (PMID 34559115, 2021). "We demonstrated the association among acute-phase MDSC recruitment, CXCL10/TLR4 overexpression, and tumor recurrence after small-for-size liver graft transplantation in both clinical and rat transplant studies." (PMID 33990548, 2021). "We suggest using Ig-based fusion proteins of two of them: CXL9 and CXCL10, to enhance anti-tumor immunity and perhaps transform cold tumors into hot tumors." (PMID 34944943, 2021). "M2 type macrophages closely resemble tumor-associated macrophages (TAMs) and are characterized by increased expression of IFN-γ, CCL2, CCL5, CXCL16, CXCL10, CXCL9, TNF-α, MMP9 and IL-10, arginase-1, and peroxisome proliferator-activated receptor-γ (PPAR-γ)." (PMID 33925575, 2021). "CXCL10 is known to play an important role in the infiltration of immune cells into the tumour bed and was previously reported to bind to CXCR3 only." (PMID 33801414, 2021). "In order to further characterize and understand the tumor immunobiology with CXCL10 expression, the construction scheme of the ovarian TME cell infiltration pattern was systematically evaluated." (PMID 34386037, 2021).
tumor (continued). "CXCL10's diverse properties are expected to make it a new strategy for targeted tumor treatment, as well as a clinical tumor prognosis indicator." (PMID 34559115, 2021). "Overexpression of CXCL10 has been shown to promote tumor growth, migration, and invasion via targeting of the cognate receptor chemokine (CXC-motif) receptor (CXCR3)." (PMID 33681290, 2021). "Under the same treatment conditions, similar results were obtained by ELISA to detect the changes in the concentration of CXCL10 in the culture supernatant of tumor cells." (PMID 34345201, 2021). "To determine the correlation between CXCL10 and tumor-infiltrated immune cells, we performed a correlation analysis by using the TIMER online website." (PMID 34276760, 2021). "Lastly, activated T cells infiltrate tumors in response to chemokines like CXCL10 and recognize the presented tumor antigens." (PMID 34206946, 2021). "CXCL10 can recruit NK cells to tumor site and activate NK cells to kill cancer cells, and it has been reported strongly produced in tumor compared with the adjacent tissue in EC." (PMID 33869285, 2021). "Blocking of CXCL10/CXCR3 signaling in vivo shifts macrophage populations to a tumor-promoting (Ym1+, Fizz+, Arg1+) phenotype, increases fibrosis, and mediates progression of lesions, highlighting the importance of this pathway in PDA development." (PMID 34328416, 2021). "The previous study reported that chemokines like CCL5 and CXCL10 can modulate tumor sensitive to immunotherapy." (PMID 33898414, 2021). "Based on the literature, these chemokines can be produced by immune cells; however, there is evidence that CXCL1, CXCL10, and IL-8 can be produced by tumor and stromal cells." (PMID 34072037, 2021). "In particular, several crucial chemokines and receptors (CXCL9, CXCL10, and CXCR3), which can recruit CD8+ T cells into the tumor microenvironment, were upregulated in the high-risk group." (PMID 34961815, 2021). "To confirm that up-regulated CXCL10 expression is derived from HRD tumor cells, we re-analyzed single-cell RNA-seq data of TNBC patients." (PMID 34158843, 2021). "We first identified that MDSCs recruited by CXCL10/TLR4 during acute phase inflammation played a critical role in tumor recurrence after liver transplantation through a series of clinical analyses, animal models, and in vitro functional experiments." (PMID 33990548, 2021). "Similar studies have shown that increases in CXCL9 and CXCL10 correlate with an enhanced infiltration of T cells, which decreases as tumours become resistant to BRAFi treatment." (PMID 34830780, 2021). "qPCR analysis revealed an increase in the expression of CXCL9 and CXCL10 chemokines from these tumor cells." (PMID 34336705, 2021). "The impact of C-7 on the levels of various cytokines (IFNγ, TNF, IL-6, and IL-10) and the chemokine CXCL10 was assessed in 1-day co-culture supernatants of dissociated CRC tumor cells and autologous PBMC." (PMID 34771609, 2021). "CXCL9 and CXCL10 were reported to promote tumor suppression by increasing immune cell differentiation, migration, and activation." (PMID 33323542, 2020). "We are now using CXCR3KO mice engrafted with CXCR3+ tumor cells to dissect the direct effect of CXCL10-Ig based therapy on tumor growth." (PMID 32547545, 2020). "Contributing mechanisms included CD4+ T cell-mediated induction of CXCL9 and CXCL10 in the tumor microenvironment to attract CXCR3-expressing CD8+ T cells or to confer a specific cytotoxic CD8+ T cell effector program amongst others." (PMID 32610710, 2020). "Presently, the elevated expression of CXCL10 in DLBCL tumor tissue samples predicted disease prognosis in DLBCL." (PMID 33240622, 2020). "In the of context adoptive cell therapy (ACT), efficacy required cDCs capable of CXCL9/CXCL10 production in order to drive tumor infiltration by the transferred T cells." (PMID 32508825, 2020).
tumor (continued). "Cxcl9 and Cxcl10 have been shown to play significant roles in recruiting Cxcr3+ T cells into the tumor and high levels correlate with improved patient survival." (PMID 32641748, 2020). "Nevertheless many human studies clearly show that in various human cancer diseases low expression/transcription of CXCL10 at tumor sites indicate poor cancer prognosis, whereas high levels of this chemokine are associated with good prognosis." (PMID 32547545, 2020). "Gram-negative bacteria produce outer membrane vesicles which induce anti-tumor responses by preferentially accumulating at the tumor site and stimulate the release of anti-tumor cytokines CXCL10 and IFN-γ." (PMID 33066447, 2020). "High levels of intra-tumoral chemokines such as CCL5, CXCL9, CXCL10 enhance the recruitment of T-cells into the tumor and preclinical studies in mice showed that infiltrating anti-tumor CD8+ T-cells are required for clinical response to anti-PD-1 treatment." (PMID 35582440, 2020). "In consonance with this result, STING knockout in LKB1-reconstituted H1355 tumor spheroids also inhibited downstream production of CXCL10." (PMID 33013881, 2020). "As for directing metastatic spread Neta Erez and her team very recently suggested that CXCL10 produced by astrocytic cells participates in chemoattraction of tumor cells to the CNS." (PMID 32547545, 2020). "As a Th1-type chemokine, CXCL10 plays an important role in determining effector T cell trafficking to the tumor microenvironment." (PMID 32430013, 2020). "In summary, to the best of our knowledge, this is the first report on the regulatory effects of in vitro autophagy inhibition on CXCL10 expression in GC cells and its potential mechanism in recruiting T lymphocytes into the tumor." (PMID 32582551, 2020). "One such agonist is 852A, which has been shown to induce CXCL10 and IL-1RA production, although minimal tumor control was observed in initial clinical trials." (PMID 32508825, 2020). "Activated Th1 lymphocytes and CTLs are able to migrate from the lymph node to the blood stream and eventually reach the tumor site in a CXCL10-dependent manner." (PMID 33281620, 2020). "Other important correlated genes included t CXCL9 and CXCL10, and they served as important regulators of immune activation in tumor microenvironment." (PMID 32231683, 2020). "In these co-cultures of tumour cells and monocytes, we detected upregulation of cytokines (TNFα, MCP-1, IL-10, CXCL-10, IL-1β, IL-6, IL-23) associated with MOv18 IgE ADCC compared to isotype control-triggered cytotoxicity." (PMID 33203088, 2020). "Individual depletion of CD4 T cells, CD8 T cells and CXCL9, CXCL10, abrogated the anti-tumor activity of combined therapy." (PMID 33167311, 2020). "Upregulation of CXCL10 can enhance the levels of Tumor-infiltrating CD8+ T cell and natural killer cells." (PMID 33330620, 2020). "We found increased CXCL10 expression but decreased CD8+ T cell infiltration in tumor tissues of advanced-stage compared with early-stage CRC patients." (PMID 32503584, 2020). "Tregs depletion leads to increased production of the CXCR3 ligand CXCL10 from endothelial cells in tumours." (PMID 32680511, 2020). "The IFN-γ-dependent chemokines CXCL9 and CXCL10 were also assessed in tumor lysates obtained from MC38 bearing-wt and IFN-γ KO mice." (PMID 32461349, 2020). "The in vivo experiment showed that BMPER was highly expressed in the early tumor growth phase (20 days), CXCL10 and HOXA9 expression was elevated with tumor progress, and spatially associated with tumor vasculature." (PMID 32432046, 2020). "Chip-seq and luciferase reporter assays showed that circMET overexpression induced an immunosuppressive tumor microenvironment via the miR-30-5p/Snail/ DPP4/CXCL10 axis." (PMID 32430013, 2020).
tumor (continued). "Hyper-activated STAT3 regulates the expression of interferon γ (IFNγ), interleukin 12 (IL-12), CD86, C-C motif chemokine ligand 5 (CCL5), and C-X-C motif chemokine ligand 10 (CXCL10) in the tumor microenvironment to promote immune evasion." (PMID 32486001, 2020). "In our work, we observed that the transcription of CXCL10 in HNSCC individuals was significantly upregulated when compared with non-tumor tissue, and the mRNA levels of CXCL10 in patients with HNSCC are related to tumor stage." (PMID 33489879, 2020). "Generally, it is accepted that CXCL10-based therapies for cancer due to its ability to attract CXCR3+ tumor-infiltrating lymphocytes (TILs) to tumor sites and sites of inflammation." (PMID 32089645, 2020). "Activated IFN-α stimulated production of the chemokine CXCL10 to recruit TILs to tumor beds and in turn initiate spontaneous antitumor T-cell response." (PMID 33194652, 2020). "We further investigated the regulatory effects of CXCL10/CXCR3 on CD8+ T cell migration using supernatants from freshly obtained CRC tumor tissues." (PMID 32503584, 2020). "PCR screening showed that CXCL10 levels were significantly increased in advanced-stage tumor tissues." (PMID 32503584, 2020). "Immunohistochemically, the expression of CCL2+ cells and CXCL10+ cells in tumor and peri-tumor were higher than in normal brain tissues, and celecoxib decreased the number of these cells." (PMID 32943658, 2020). "Previous studies determined the upregulation of genes related to immune cell activation (e.g., CD3D, CD8, CXCR3, CCL5, CXCL9, and CXCL10) in cancer patients with a better prognosis, thereby highlighting the impacts of immune-related genes on tumor progression." (PMID 32775427, 2020). "We then performed qRT-PCR in SFE-treated ESCC cells and ground tumor lumps from the previous xenograft tumor assay, verifying that the expression of CXCL10, TNFAIP3, INHBA, and PLAU was indeed controlled by SFE in ESCC." (PMID 33374641, 2020). "In accordance with the literature, CXCL9 or CXCL10 depletion abolished the anti-tumor efficacy of combined therapy." (PMID 33167311, 2020). "The transcriptional profiling of the tumor models used in this study revealed increased levels of the chemokines Cxcl9 and Cxcl10 in tumors from Aire−/− mice." (PMID 32641748, 2020). "This is plausible given that miR-181a overexpression decreased secretion of CXCL10, an important chemokine necessary for immune cell recruitment (and subsequent activation) to the tumor microenvironment." (PMID 32591511, 2020). "TNFα, MCP-1 and IL-10, which we previously reported to be enhanced in the tumour microenvironment following systemic IgE treatment in vivo, were secreted by monocytes alongside immune mediators CXCL-10, IL-4, IL-1β and IL-23." (PMID 33203088, 2020). "In this study, we demonstrated that intra-tumor CXCL10 is an important chemokine that contributes to intra-tumor infiltration of T lymphocytes in GC." (PMID 32582551, 2020). "By binding to IFNα and IFNβ receptors (IFNARs) on tumor cells, type I IFNs trigger autocrine and paracrine circuitries to promote the release of chemokine (C-X-C motif) ligand 10 (CXCL10)." (PMID 32326356, 2020). "Mechanistically, it has been proposed that EZH2-mediated gene silencing of chemokines, such as CXCL9 and CXCL10, prevents effector T-cell trafficking to the tumor microenvironment, thereby allowing tumor cells to evade immunity." (PMID 33374737, 2020). "Of note, CXCL9 and CXCL10 recruiting pro-tumor immature CD56brightCD16low/neg NK cells are also involved in the recruitment of cytotoxic CD8 T cells." (PMID 33262763, 2020). "On the other hand, an in vitro study showed that monocytes, orchestrated by CXCL10, promote the migration and invasion of tumor cells in B cell precursor acute lymphoblastic leukemia (ALL), and then stimulate metastasis." (PMID 31991604, 2020). "Currently much attention is given to CXCL9 and CXCL10 and their role in the potentiation of anti-tumor CD8+ T cells." (PMID 32547545, 2020).